TRAJ45 (T cell receptor alpha joining 45)
Gene: T-cell receptor joining (J) gene on chromosome 14 (22,493,925 to 22,493,990, forward strand). Ensembl gene ENSG00000211844.
Diseases named in the same sentence as TRAJ45 in open-access papers:
TRAJ45 is named in the same sentence as 1 disease in open-access papers, as found by Europe PMC text mining. Sharing a sentence is not in itself a finding about the gene and the disease.
TRAJ45 shares sentences with these, for which no sentence is quoted: COVID-19 (1 paper).